RIOK3 (RIO kinase 3)
Description:
Serine/threonine-protein kinase involved in a ribosome quality control that takes place when ribosomes have stalled, leading to 18S non-functional rRNA decay and degradation of the 40S ribosomal subunit. Acts downstream of RNF10: specifically recognizes and binds RPS2/us5 and RPS3/us3 monoubiquitinated by RNF10, promoting degradation of the 40S ribosomal subunit in a kinase-dependent manner. The RNF10-RIOK3 ribosome quality control takes place in response to ribosome subunit imbalance or downstream the EIF2AK4/GCN2-mediated integrated stress response (ISR). Also involved in regulation of type I interferon (IFN)-dependent immune response, possibly by acting as an adapter protein essential for the recruitment of TBK1 to IRF3. Phosphorylates IFIH1 on 'Ser-828' interfering with IFIH1 filament assembly on long dsRNA and resulting in attenuated IFIH1-signaling. Can inhibit CASP10 isoform 7-mediated activation of the NF-kappa-B signaling pathway.
Synonyms: SUDD
Tractability: Small molecule: a high-quality ligand is known; it belongs to a druggable protein family. Antibody: the Human Protein Atlas places it where antibodies can reach. PROTAC: ubiquitination databases record sites on it; its protein half-life has been measured; a small molecule that binds it is known.
Target class: Atypical protein kinase group; Enzyme; Kinase; Protein Kinase; Atypical protein kinase RIO family; Atypical protein kinase RIO3 subfamily
Gene: Protein-coding gene on chromosome 18 (23,453,280 to 23,486,603, forward strand). Ensembl gene ENSG00000101782.
Subcellular location: Cytoplasm, cytosol
Subcellular location (Human Protein Atlas): Cytosol; Plasma membrane; Centriolar satellite; Golgi apparatus
Pathways (Reactome):
Metabolism of RNA: Major pathway of rRNA processing in the nucleolus and cytosol
Gene Ontology:
Molecular function: caspase binding; protein binding; protein serine kinase activity; protein serine/threonine kinase activity; ubiquitin-modified protein reader activity; ATP binding; catalytic activity
Biological process: cellular response to dsDNA; cellular response to dsRNA; cellular response to virus; maturation of SSU-rRNA; negative regulation of canonical NF-kappaB signal transduction; negative regulation of MDA-5 signaling pathway; negative regulation of protein-containing complex assembly; nonfunctional rRNA decay; positive regulation of innate immune response; positive regulation of interferon-beta production; ribosome-associated ubiquitin-dependent protein catabolic process; chromosome segregation
Cellular component: cytosolic ribosome; preribosome, small subunit precursor; cytosol
Genetic constraint (gnomAD): Loss-of-function variants: 19 observed, 30.76 expected, observed/expected ratio (o/e) 0.62, 90% interval 0.43 to 0.91. The upper end of that interval is the gene's LOEUF score, 0.91, which puts it in group 3 of 6, group 1 being the genes least tolerant of losing a copy. Missense variants: 290 observed, 333.68 expected, observed/expected ratio (o/e) 0.87, 90% interval 0.79 to 0.96. Synonymous variants: 97 observed, 113.23 expected, observed/expected ratio (o/e) 0.86, 90% interval 0.73 to 1.01.
Homologues: Orthologues: chimpanzee RIOK3 (99% identical), macaque RIOK3 (99% identical), dog RIOK3 (96% identical), pig RIOK3 (96% identical), rabbit RIOK3 (95% identical), guinea pig RIOK3 (94% identical), rat Riok3 (94% identical), mouse Riok3 (94% identical), tropical clawed frog riok3 (76% identical), zebrafish riok3 (71% identical), Drosophila melanogaster CG3008 (43% identical), Caenorhabditis elegans riok-3 (35% identical). Paralogues in human: RIOK1 (31% identical), RIOK2 (13% identical), ATMIN (12% identical).
Diseases named in the same sentence as RIOK3 in open-access papers:
RIOK3 is named in the same sentence as 27 diseases in open-access papers, as found by Europe PMC text mining. Sharing a sentence is not in itself a finding about the gene and the disease. The quoted sentences say what the papers report.
viral infection (10 papers, 2019 to 2025). "In conclusion, we show that the transcript encoding RIOK3, an incompletely understood immune regulatory protein, can be rendered nonfunctional by an alternative splicing event that is triggered by viral infection or other innate immune stimuli." (PMID 33652597, 2021). "We have observed that the effect of diminished STAT1 phosphorylation in the RIOK3-KO cells is most pronounced at the 24-h post virus infection." (PMID 40371100, 2025). "Consistent with our previous study, the increased production of IFN-α and IFN-β in RIOK3-KO macrophages highlights the importance of RIOK3 in negatively regulating the induction of type I IFNs following viral infection." (PMID 40371100, 2025). "We previously identified RIOK3, a phosphorylating kinase, as a pivotal regulator of viral infection in macrophages through siRNA screening." (PMID 40371100, 2025). "During viral infection, m6A modification of RIOK3 promotes its translation, while reduced m6A modification of CIRBP promotes alternative splicing." (PMID 39072324, 2024). "Research has demonstrated that ER stress responses activated by viral infection are involved in m6A changes in RIOK3 or CIRBP." (PMID 39072324, 2024). "Propagation of RVFV strain MP-12 is negatively impacted by the actions of RIOK3, a protein involved in the cellular immune response to viral infection." (PMID 35127560, 2021). "In any case, the clearly important roles of RIOK3 during viral infection warrants additional investigation." (PMID 33652597, 2021). "RIOK3 was particularly intriguing since two previous studies suggested it is involved in the innate immune response that is important for controlling viral infection." (PMID 33652597, 2021). "By demonstrating that RIOK3 has different effects in separate innate immune pathways, qualitative or quantitative changes to its expression during viral infection could very well lead to dysregulated innate immune responses that are harmful to the host and/or are designed to enhance viral success." (PMID 36146870, 2022). "Thus, RIOK3 may act in dual roles, both as an effector and an inhibitor of innate immune responses to viral infection, depending on the cell type, virus type, and the immune pathway that has been activated." (PMID 35127560, 2021). "RIOK3 and IFIH1 are involved in IFN-dependent immune responses and play critical roles in sensing viral infections and activating antiviral cascades." (PMID 40783707, 2025). "Upon viral infection, TRA2-β is alternatively spliced, decreasing its cellular levels, forcing the RIOK-3 mRNA to undergo alternative splicing and produce the variant isoform RIOK-3 X2." (PMID 37242305, 2023). "A statistically significant increase in promoter activity was observed in RVFV-infected RIOK3 KO cells compared to RVFV-infected WT cells, suggesting endogenous RIOK3 mitigates activation of the inflammatory response during viral infection." (PMID 36146870, 2022). "Specifically, we aim to investigate whether RIOK3 participates in the JAK1/STAT1 pathway, which is central to the interferon response to viral infections." (PMID 40371100, 2025). "To assess the impact of RIOK3 on RSV replication, we measured RSV-F mRNA expression, type I interferons (IFN-α and IFN-β) production, and several inflammatory factors in control and RIOK3-KO macrophages at various time points during viral infection." (PMID 40371100, 2025). "A separate report showed that RIOK3 acts as an adaptor protein that mediates the interaction between IRF3 and TBK1 downstream of PRR activation, which is critical for type I IFN induction following viral infection." (PMID 33652597, 2021). "Therefore, further understanding of the onset of alternative splicing of RIOK3 during activation of the noncanonical NFκB pathway could be important for both understanding how innate immune responses are regulated and how they can be dysregulated during viral infection and other disease states." (PMID 37515252, 2023).
viral infection (continued). "Although the mechanism for how expression of the truncated form of RIOK3 exerts an effect in the IFN and NFκB pathways is not yet fully understood, this event does appear to be consequential for the cell during viral infection, and could contribute to pathology." (PMID 36146870, 2022).
glioma (4 papers, 2020 to 2022). A benign or malignant brain and spinal cord tumor that arises from glial cells (astrocytes, oligodendrocytes, ependymal cells). "In addition, our recent work has found that down‐regulation of RIOK3 causes G1 arrest, whereas overexpression of RIOK3 accelerates cell cycle progression in glioma cells." (PMID 32125767, 2020). "The high RIOK3 level in glioma promotes the proliferation, migration, and invasion of glioma cells through the AKT/mTOR pathway." (PMID 35281872, 2022). "Overexpression of RIOK3 has opposite effects on the proliferation, migration, invasion of glioma cells, and the AKT/mTOR signal transduction pathway." (PMID 34138931, 2021). "High RIOK3 levels in gliomas contribute to proliferation, migration, and invasion of glioma cells." (PMID 35280808, 2022). "Stable overexpression of RIOK3 promotes proliferation, invasion and migration of glioma cells, while silencing of RIOK3 inhibits proliferation, migration and invasion, and induces apoptosis in glioma cells." (PMID 32125767, 2020). "RIOK3 promotes growth, survival, migration and invasion of glioma cells." (PMID 32125767, 2020). "Down-regulation of RIOK3 significantly reduced the AKT/mTOR signaling pathway activity and induced apoptosis of glioma cells." (PMID 34138931, 2021).
breast carcinoma (2 papers, 2014 to 2025). "Other genes, including ATP5A, BCR, FGFR4, PDPK1, PIP5K1C, RIOK3, and SRC, also act to regulate TRAIL-induced apoptosis, but their potential to overcome resistance to TRAIL-induced cytotoxicity when inhibited may be more context specific (that is, in a more-restricted subset of breast cancer cells)." (PMID 24745479, 2014).
co-infection (2 papers, 2022 to 2024). "Further studies are needed to map the RIOK3 phosphorylation site of Akt to further explore the role of RIOK3-Akt pathway in viral replication, pathogenesis, and tumorigenesis during co-infection of MDV and REV." (PMID 35795905, 2022). "Here, we found that co-infection of REV and MDV increased their replication via the RIOK3-Akt pathway." (PMID 35795905, 2022).
Alzheimer disease (1 paper, 2022). A progressive, neurodegenerative disease characterized by loss of function and death of nerve cells in several areas of the brain leading to loss of cognitive function such as memory and language. "Among the top 10 DMP genes, we found two of them were related to mental health disorders: RIOK3 (cg21515243) was a gender-specific risk factor for Alzheimer’s disease and PSMB4 (cg01334186) involved inflammation was related to the susceptibility to major depression." (PMID 36344488, 2022). "For example, the DMP gene RIOK3 and the DMR gene USP6NL (overlapped DMR gene between case-control study and GAD vs OCD study) were the risk genes for Alzheimer’s disease." (PMID 36344488, 2022).
autoimmune disease (1 paper, 2021). A disorder resulting from loss of function or tissue destruction of an organ or multiple organs, arising from humoral or cellular immune responses of the individual to their own tissue constituents. "Because overstimulation of innate immunity can lead to cell death and tissue damage and can lead to autoimmune disease, we hypothesized that RIOK3 splicing may modulate the immune/inflammatory response after an initial robust reaction to pathogen incursion." (PMID 35127560, 2021).
colon cancer (1 paper, 2024). "Collectively, our findings suggest that RIOK3 sustains colon cancer cell survival in low-glucose environments through an HSP90α-dependent pathway." (PMID 38453884, 2024).
colorectal cancer (1 paper, 2024). A primary or metastatic malignant neoplasm that affects the colon or rectum. "This study highlights the crucial role of RIOK3 in maintaining NADPH production and colorectal cancer (CRC) cell survival during glucose deficiency." (PMID 38453884, 2024).
head and neck cancer (1 paper, 2013). A primary or metastatic malignant neoplasm affecting the head and neck. "The increased expression of RIOK3 has been observed in metastatic head and neck cancers compared with nonrecurrent tumors." (PMID 24377043, 2013).
pancreatic adenocarcinoma (1 paper, 2010). "For some of these genes putative roles in pancreatic adenocarcinoma progression have been identified, as RIOK3 and MEMO1 or in tumor angiogenesis such as TBK1." (PMID 20553613, 2010). "Numerous genes were overexpressed, some of which have previously been implicated in pancreatic adenocarcinoma (GATA6, IGFBP3, IGFBP6), while others were detected for the first time (MEMO1, RIOK3)." (PMID 20553613, 2010).
pancreatic cancer (1 paper, 2025). "In our experiments, stable overexpression of RIOK3 (even in combination with TUFT1) did not restore the effect of ZIC5 suppression in MiaPaca‐2 cells, suggesting that other ZIC5 downstream genes also contribute to pancreatic cancer survival." (PMID 40318167, 2025).
parasitemia (1 paper, 2024). "Three modules led by the hub genes RIOK3, CSDE1, and SEC62 negatively associated with protection and positively associated with both prevaccination anti–CSP IgG and parasitemia at first vaccination." (PMID 38687615, 2024).
rectal cancer (1 paper, 2022). A primary or metastatic malignant neoplasm that affects the rectum. "In our study, CYP1B1, ANO1, and RIOK3 were negatively associated with prognosis and nCRT response in rectal cancer." (PMID 36505493, 2022).
infection (12 papers, 2017 to 2025). The state of being infected such as from the introduction of a foreign agent such as serum, vaccine, antigenic substance or organism. "Here, we characterize RIOK3 as an important component of the interferon signaling pathway during RVFV infection and demonstrate that RIOK3 mRNA expression is skewed shortly after infection to produce alternatively spliced variants that encode premature termination codons." (PMID 33652597, 2021). "Meanwhile, Western blot (WB) results revealed a slight increase in RIOK3 protein levels at early time points, followed by a decrease at later stages of infection." (PMID 40371100, 2025). "As RSV-F expression increased over time, a significant upregulation of RIOK3 mRNA was observed at 2-, 4-, and 6-h post-infection (hpi) compared to uninfected controls." (PMID 40371100, 2025). "The marked change in the splicing pattern of RIOK3 mRNA upon infection or treatment with poly (I:C) or 3p-hpRNA is intriguing." (PMID 33652597, 2021). "Of particular interest, we observed that the host mRNA for Rio Kinase 3 (RIOK3) was alternatively spliced during infection." (PMID 33652597, 2021). "In the context of infection by Flaviviridae, RIOK3 methylation, and CIRBP demethylation took place, and the changed m6A status promoted translation of RIOK3 and alternative splicing of CIRBP, respectively, all benefiting Flaviviridae infection consequently." (PMID 34975810, 2021). "Our prior transcriptome profiling study of RVFV MP-12-infected cells indicated that RIOK3, a host factor recently characterized as an important player in the host antiviral response, is alternatively spliced during infection." (PMID 33652597, 2021). "In the present study, we show that RIOK3 acts in an antiviral capacity during RVFV MP-12 infection and plays a critical role in activation of IFN signaling." (PMID 33652597, 2021). "Interestingly, RIOK3 has been implicated as an important player in the host antiviral response and thus this splicing event could have important regulatory consequences for these pathways post-infection." (PMID 31136639, 2019). "Therefore, we conclude that overexpression of RIOK3 X2 during RVFV MP12 infection elevates p100 expression with a concomitant decrease in IFNβ expression." (PMID 37515252, 2023). "Previously, we showed the atypical kinase RIOK3 is important for mounting an IFN response to RVFV infection of human epithelial cells, and shortly following infection with RVFV (MP12 strain), RIOK3 mRNA is alternatively spliced to its X2 isoform that encodes a truncated RIOK3 protein." (PMID 37515252, 2023). "If RIOK3 plays a role in expression of secreted cytokines, media from stimulated cells lacking RIOK3 should stimulate a less robust response against subsequent infection." (PMID 36146870, 2022). "Furthermore, Gokhale and colleagues reported that RIOK3 is required for productive infection of Dengue virus and Zika virus, but is inhibitory towards hepatitis C virus." (PMID 33652597, 2021). "In contrast, infection with Adenovirus, a double-stranded DNA virus, did not promote RIOK3 X2 variant alternative splicing." (PMID 33652597, 2021). "Our observation that overexpression of full length RIOK3 makes wild type cells modestly more resistant to infection is consistent with its role in a pathway(s) in which both the abundance and the cellular activation of the components of the pathway are essential to observe the response." (PMID 33652597, 2021). "Either possibility suggests that RIOK3 expression could be regulated qualitatively and/or quantitatively at the level of alternative splicing in order to fine-tune the host response to infection." (PMID 33652597, 2021). "Our prior work showed that RIOK3 alternative splicing increased during RVFV MP-12 infection." (PMID 33652597, 2021).